MCL1 (MCL1 apoptosis regulator, BCL2 family member)
Diseases named in the same sentence as MCL1 in open-access papers (continued):
Sharing a sentence is not in itself a finding about the gene and the disease.
tumor (continued). "Inhibition of ERK-, JNK- or Akt-mediated Mcl-1 stability may confer Bcl-2 inhibitor better anti-tumor effect in HCC cells." (PMID 24779770, 2014). "Interestingly, recent studies have identified that cyclooxygenase-2 inhibitors can induce apoptosis and anti-tumor activities through down-regulation of OPN as well as Mcl-1." (PMID 24947165, 2014). "Validation that MCL1 downregulation is a major mechanism of dinaciclib's effect was further supported by observing the greatest efficacy effect in the highly MCL1-dependent NCI-H23 xenograft tumor model." (PMID 25289887, 2014). "Importantly, Huh7 tumor-bearing nude mice treated with SC-2001 showed downregulation of Mcl-1 and p-STAT3 protein expression and upregulation of SHP-1, LC3II, and RFX-1 protein expression." (PMID 24952874, 2014). "It is therefore reasonable that the expression of the anti-apoptotic protein Mcl-1, is not directly associated with mitotic rate and tumor size, two major reliable indicators and poor prognostic factors for tumor proliferation, growth, and progression in GIST." (PMID 24947165, 2014). "Finally, Mcl-1 was expressed in a high proportion of tumor cells of all studied xenografts, except for the MM66 xenograft, but with a relative weak intensity." (PMID 24454684, 2014). "While dinaciclib treatment caused tumor regression in the NCI-H23 xenograft model, the other three MCL1:BCL-xL high mRNA ratio xenograft models (COLO 320DM, A2780 and 22Rv1) showed only ∼40–50% tumor growth inhibition, despite apoptosis induction within the tumors." (PMID 25289887, 2014). "Furthermore, Mcl-1 overexpression was significantly associated with OPN and β-catenin expression in tumor tissues, as well as worse survival clinically." (PMID 24947165, 2014). "Furthermore, PIAS1 knockdown leads to increased expression of the cell cycle inhibitor p21 and to reduced Mcl1 levels, thereby resulting in induced apoptosis of parental and docetaxel resistant tumor cells." (PMID 25474038, 2014). "In tumour cells, roscovitine induces apoptosis that is accompanied by down-regulation of the anti-apoptotic Bcl-2-family member Mcl-1, and roscovitine also down-regulates Mcl-1 in neutrophils." (PMID 24223929, 2013). "IP western blotting was next applied to determine whether JY-1-106 could effectively disrupt the binding between Bak and anti-apoptotic proteins Bcl-xL and Mcl-1 in tumor cells." (PMID 23680104, 2013). "On the contrary, the miR-29a/29b cluster could promote GIC apoptosis and also improve bulk tumor killing in GBM by targeting MCL1, being a promising candidate to design future treatments for GBM aimed to avoid recurrence." (PMID 24155920, 2013). "Moreover, WP1130 has also been found to promote Mcl-1 degradation and increases tumor cell sensitivity to chemotherapies in colon adenocarcinomas and lung cancers." (PMID 24152793, 2013). "Cell lines and tumours expressing high Mcl-1 levels are resistant to ABT-737." (PMID 22240779, 2012). "As targeting of several antiapoptotic proteins simultaneously was found to enhance apoptosis, we tested whether inhibition of one antiapoptotic Bcl-2 protein together with either Mcl-1 or A1 is able to enhance apoptosis induction in a tumor-specific manner." (PMID 22292048, 2012). "So far, limited information is available on the role of Mcl-1 in radiation response of tumor cells." (PMID 22873792, 2012). "The up-regulation of Mcl-1 in HCC cells could inhibit chemotherapeutic drug-induced apoptosis of tumor cells." (PMID 22942733, 2012). "Thus ABT-737 is ineffective in killing tumor cells expressing high levels of Mcl-1 compared with those of Bcl-2/Bcl-xL." (PMID 22703841, 2012). "In addition, the blocking of USP9X activities using a small-molecule inhibitor decreases Mcl-1 expression by promoting its degradation and thus sensitizes tumor cells to chemotherapeutic agents." (PMID 23171055, 2012).
tumor (continued). "We next examined whether cell death induced by inhibition of A1, Mcl-1, or both, can further be enhanced by exposure to chemotherapy, i.e., 5-fluorouracil (5-FU), while maintaining the tumor specificity." (PMID 22292048, 2012). "Among the genes participating in the cascade of signal transfer in cell activated by leptin, the following ones: AKT1, STAT3, MCL1 were qualified as differentiating stage I and II and VEGFC, CCNDI the encoding genes respectively as differentiating III and IV stage neoplasm." (PMID 22363883, 2011). "Interestingly, the down regulation of Mcl-1 by sorafenib has been shown previously in other tumor models." (PMID 22206574, 2011). "The Bax:Mcl1 ratio might become a clinically-important molecular prognosticator of tumor response to TW-37 since, in this study, it correlated positively with TW-37-induced apoptosis." (PMID 19220884, 2009). "Indeed, suppression of Mcl-1 protein levels by shRNA knockdown or indirect pharmacological downregulation sensitizes resistant tumor cells to ABT-737 mediated cell death." (PMID 19209227, 2009). "In non-tumor liver tissue adjacent to HCC Mcl-1 immunoreactivity was significantly lower." (PMID 17014711, 2006). "Importantly, we found that in the setting of venetoclax resistance, continuing venetoclax may be counter-productive, as it may further stabilize the anti-apoptotic protein MCL-1 and promote tumor growth." (PMID 41484790, 2026). "Thus, loss of the LKB1 tumor suppressor is associated with increased MCL-1 dependence upon treatment with sotorasib or trametinib in KRASG12C-mutant NSCLCs, creating an apoptotic vulnerability that can be exploited by concurrent inhibition of MCL-1." (PMID 40316540, 2025). "However, high MCL-1 expression did not demonstrate significant associations with well-established prognostic factors, including tumor location and liver enzyme level (ALT and AST)." (PMID 40380182, 2025). "Indeed, due to venetoclax’s specific targeting of Bcl-2, tumor cells may shift their dependency to other anti-apoptotic proteins such as Bcl-XL, MCL-1 and Bfl-1 for survival." (PMID 40400713, 2025). "Additionally, FLT3 inhibitors may modulate BCL-XL and MCL-1 expression, increasing the dependence of tumor cells on BCL-2 and potentially enhancing the efficacy of venetoclax." (PMID 40016600, 2025). "Finally, we investigated the impact of MCL1 inhibition on tumor growth in vivo." (PMID 40841513, 2025). "Interestingly, 51% (60/118) of pHGG tumor cores exhibited moderate-high MCL1 staining (score ≥ 2) compared with adult tumors, where only 35% (25/71) of the cores expressed moderate-high levels of MCL1 (P = 0.04)." (PMID 39846250, 2025). "Previous studies have shown that adaptation of tumor cells to VEN is characterized by different mechanisms resulting in functional loss of pro-apoptotic regulators like BAD, BAX, NOXA and PUMA or by a shift in dependency from BCL-2 to other anti-apoptotic proteins like MCL-1." (PMID 38961053, 2024). "However, MCL1 activity in tumor cells varies depending on transcriptional and cellular contexts." (PMID 39122703, 2024). "Consistent with this hypothesis, we found that multiple BCL2 proteins are transcribed in the primary tumor and early, midpoint, and late metastases, with MCL1 being significantly more abundant compared to other anti-apoptotic factors regardless of the time point." (PMID 37676378, 2024). "While we acknowledge proteomic analysis of these patient samples could be skewed by components of the tumor immune microenvironment, BRAFi resistance may at least in part be attributed to a Mcl-1 regulated minority MOMP-like phenotype, paralleling our observations of MDA-T32." (PMID 38622136, 2024). "Interestingly, in a clinical trial against relapsed or refractory hematological malignancies, some MCL1 inhibitors were reported to promote on-target/off-tumor toxicity, and in that trial, administration of the MCL1 inhibitor AMG-397 was suspended due to cardiac side effects." (PMID 39122703, 2024).
tumor (continued). "It was shown that tumor regression in STAT3 shRNA lentivirus Ly3-bearing mice was associated with Caspase-3-dependent apoptosis and significant decrease of STAT3 target genes encoding MCL1, C-MYC, and survivin, as well as inhibition of tumor-promoting environment." (PMID 39528914, 2024). "Additionally, we revealed that the reduction in tumor growth might be linked to the downregulation of proteins involved in tumor progression like EGFR and STAT3 and anti-apoptotic proteins like Mcl-1 via dinaciclib." (PMID 39668430, 2024). "USP13 is a member of the DUBs family and plays key roles in various biological processes including tumor promotion, inflammation, apoptosis, drug resistance and anti-viral responses by cleaving ubiquitin molecules from associated proteins including STING, Myc, PTEN and Mcl-1." (PMID 36915206, 2023). "In contrast to the epithelial cells, carboplatin treatment led to increased expression of pro-survival factors (Bcl2, Mcl1, Ier3, Ier5, Hmox1) in stromal cell populations, thus preserving their viability and potentially providing a means of stabilizing and prolonging the anti-tumor response." (PMID 37660083, 2023). "Indeed, miR-15/16 are known tumor suppressors, best characterized in B cell leukemia, which affect cell growth by restricting cell-cycle and anti-apoptotic genes such as Ccnd1 (cyclin D1), Bmi1, Bcl2, and Mcl1." (PMID 37862171, 2023). "Here, (R,S′)-MNF exerted a potent repression of the Hippo-YAP/TAZ signaling in PANC-1 tumor xenografts with the downregulation of genes encoding key mediators (TAOK1, MST2, MOBK1B), transcriptional regulators (WWTR1, TEAD4), and downstream pro-survival genes CYR61, BIRC2, and MCL1." (PMID 35256673, 2022). "In addition, further functional assays showed that FGD5-AS1 promotes OC progression through the miR153-3p/MCL1 axis, and overexpression of miR153-3p or inhibition of MCL1 could reverse the tumor-promoting effect of FGD5-AS1." (PMID 35475392, 2022). "Furthermore, treatment with different Mcl-1 inhibitors resulted in the effective removal of senescent tumor cells and the complete abrogation of the bystander migratory phenotype, orchestrated by the SASP on non-senescent tumor cells, both in transgenic and xenograft models." (PMID 35449130, 2022). "The results indicate that AITC decreased the levels of myeloid cell lymphoma-1 (MCL-1), matrix metalloproteinase-9 (MMP-9), vascular endothelial growth factor (VEGF), and X-linked inhibitor of apoptosis (XIAP), and increased the expression of caspase-3, -8, and -9 in tumor sections." (PMID 36142326, 2022). "Beyond apoptosis, Mcl-1 also regulates autophagy and may promote survival of tumor cells." (PMID 36045907, 2022). "Therefore, BCL-XL plays a greater role than MCL-1 in the drug resistance of tumour cells." (PMID 35598030, 2022). "Specific targeting of MCL1 may overcome the antiapoptotic ability of malignant tumor cells." (PMID 36262872, 2022). "We hypothesize that this bicalutamide-pretreated tumor had relative enzalutamide resistance associated with baseline RB1 loss and quickly developed increased RTK signaling and suppressed apoptotic response (MCL1 gains) on enzalutamide." (PMID 34568716, 2021). "Furthermore, we confirmed that circPVT1 could regulate Myeloid cell leukemia-1 (MCL-1) expression by sponging to miR-339-3p, which affected tumor progression in GBC cells." (PMID 34312371, 2021). "Additionally, the tumor suppressor miR-451 was also shown to enhance cisplatin sensitivity via regulation of Mcl-1 expression, suggesting that novel therapeutic targets may be designed thereafter." (PMID 34680465, 2021).
tumor (continued). "Potentially, if a safe therapeutic window can be established, co-dosing of AZD0466 with an MCL-1 inhibitor could be feasible, and presents an attractive strategy, especially given that we and others, have shown that optimal tumor cell killing can be achieved with BCL-XL and MCL-1 co-inhibition." (PMID 34050131, 2021). "Thus, CircMTO1 mediated human granulosa-like tumor cell progression through the miR-320b/MCL1 axis." (PMID 34413875, 2021). "Therefore, MCL-1 is a very promising target for tumor treatment." (PMID 33883020, 2021). "Finally, approaches that selectively cause robust ISR activation in tumor cells, with increased NOXA and MCL1 degradation, may create an exploitable therapeutic window for BCLXL antagonists." (PMID 32484436, 2020). "Furthermore, miR-133b was observed to be capable of attenuating the expression level of its targets (i.e., Met, BCL2L2, IGF1R, and MCL-1) and may serve as a tumor suppressor in OS." (PMID 32565738, 2020). "Therefore, MCL1 has become one of the effective targets for tumor treatment." (PMID 32675387, 2020). "In vitro data showed that a shift in splicing from Mcl-1L to Mcl-1S induced by treatment with Mcl-1-specific steric-blocking oligonucleotides (SBOs) efficiently decreased Mcl-1L expression, increased Mcl-1S expression, and accelerated tumor cell apoptosis in a dose-dependent manner." (PMID 33052877, 2020). "Finally, MCL-1 is not only important for tumor development and initial drug sensitivity." (PMID 33308268, 2020). "Furthermore, irrespective of tumor type, Mcl-1 upregulation has been associated with high tumor grade and a decrease in patient survival." (PMID 31404252, 2019). "In addition, knockdown of MCL‐1 inhibits tumour growth in GC cells in vivo." (PMID 31497917, 2019). "Hence tumours that are normally unresponsive to ABT-263 may become amenable to treatment when combined with drugs which either repress MCL-1 or induce MCL-1 antagonist NOXA." (PMID 29580266, 2018). "Importantly, in addition to apply genetic approaches to modulate USP13 expression, we have tested a preclinical lead compound spautin-1 and evaluated the impact of pharmacologically inhibiting USP13 activity on MCL1 protein expression and tumor cell sensitivity to ABT-263." (PMID 29335437, 2018). "In addition, we explored whether pharmacological inhibition of USP13 downregulated MCL1 protein expression and synergistically kill tumor cells in combination with ABT-263." (PMID 29335437, 2018). "To determine whether the expression levels of these genes have predictive value, we used a sliding scale analysis to identify threshold expression levels of BCL-XL and NOXA that best segregated tumor cell lines on the basis of MCL-1 or BCL-XL dependency, respectively." (PMID 30158527, 2018). "Taken together, PEITC can diminish the ectopic xenograft tumor growth of GBM 8401 cells in tumor weights and volumes, which may be through the induction of apoptosis by the decrease of anti-apoptotic proteins MCL-1 and XIAP, and the increase of pro-apoptotic proteins caspase-3 and Bax." (PMID 30201893, 2018). "We next determined whether knockdown of MCL-1 could suppress tumor growth in vivo." (PMID 28659182, 2017). "There are also reports about MCL1 and tumor metastasis, although the mechanism remains unclear." (PMID 28881590, 2017). "To investigate this hypothesis, we detected the expression of MCL-1 in T-47D tumor tissues." (PMID 28423543, 2017). "However, only a few reports exist on the use of ABT-263 or ABT-737 in hypoxic tumor models, and as pointed out by Harrison and co-workers, whether Mcl-1 is up- or down-regulated may be cell type- and oxygen concentration-dependent." (PMID 27461218, 2016). "In addition, we detected the levels of MCL-1 in these tumor xenografts." (PMID 26918349, 2016).
tumor (continued). "However, tumor cells that survived the treatment exhibited overexpression of Mcl-1." (PMID 26497853, 2015). "Additionally, cellular and tumor models, dependent on Mcl-1 for survival, were employed." (PMID 26231047, 2015). "In summary, this shows that MCL1 is increasingly expressed and plays a role in the fate of cells in several compartments within PCa tissue and indeed that it could play an important role in PCa tumor initiation." (PMID 25749045, 2015). "Indeed, STAT3-dependent tumor transformation usually correlates with enhanced expression of anti-apoptotic and pro-proliferative genes such as Bcl-2, MCL-1, cyclin-D1, and c-myc, which help preventing apoptosis and stimulating tumor growth, migration, and invasion." (PMID 26106584, 2015). "However, both molecules drive Mcl-1 to high levels within tumor cells." (PMID 26008975, 2015). "It has been reported that aberrant STAT3 activation promotes uncontrolled tumor cell growth and survival through multiple mechanisms, including increased expression of oncogenes, such as c-myc, Skp2, and cyclin D1, as well as antiapoptotic proteins, including Bcl-2, Bcl-xL, Mcl-1, and survivin." (PMID 24386318, 2013). "However, when targeting two antiapoptotic Bcl-2 proteins simultaneously, the approach to identify tumor-specific combinations turned out to be very important: Inhibition of Mcl-1 in combination with the inhibitor ABT-737 strongly induced cell death, which was also observed by others." (PMID 22292048, 2012). "It has also been reported that ERK-mediated phosphorylation is an important regulator of Mcl-1 stability, and downregulation of Mcl-1 is one of the main antitumor effect of sorafenib, either alone or in combination with other agents, on several kinds of tumor cells." (PMID 22520038, 2012). "Thus, ABT-737 may be active also in HB tumours, as gene expression analysis revealed a 2-fold lower expression of Mcl-1 in native HB tissue than in normal liver tissue." (PMID 21854558, 2011). "Furthermore, there was a trend towards increased Mcl-1 levels with increased tumor depth." (PMID 19684859, 2009). "Tumour cells often escape cell death by overexpressing anti-apoptotic members of the BCL-2 protein family, particularly BCL-2, BCL-xL, and MCL1." (PMID 41937490, 2026). "Co-cultures with CD40L-expressing stromal cells, mimicking the tumor microenvironment (TME), induced resistance to BCL2 and BCLXL targeting BH3-mimetics via cell-type specific upregulation of BCLXL or MCL1." (PMID 40819126, 2025). "Here, we provide evidence from both in vitro and in vivo experiments, employing a wide range of GC cell lines, patient-derived tumor organoids (PDOs) as well as CDX and PDX xenograft models, to demonstrate that BCLXL and MCL1 are key for GC cell survival." (PMID 40075071, 2025). "In the Mito-FF treatment group, the tumor tissue exhibited a significant increase in the pro-apoptotic marker, cleaved PARP, compared to the control group, while the anti-apoptotic marker, Mcl-1, showed a significant decrease (p < 0.05)." (PMID 39859498, 2025). "Various BCL-2, BCL-xL, and MCL-1 inhibitors induce apoptosis in NB cells, and BCL-2 mRNA and protein levels are increased in ALKF1174L/MYCN NB tumours compared to tumours with only MYCN amplification." (PMID 41511287, 2025). "FL496-treated MPM cells resulted in strong inhibition of the expression of survivin, Mcl-1, Bcl-2, Bcl-XL, and the induction of active caspase-3, cleaved PARP, and PUMA, which were further confirmed using MPM tumor tissues via IHC analysis." (PMID 41121175, 2025). "High-risk patients responded better to AZD5991-1720, an MCL1 inhibitor, while low-risk patients showed improved responses to IGF1R-3801-1738, an IGF1R inhibitor, suggesting that risk stratification may help optimize treatment selection based on tumor-specific vulnerabilities." (PMID 40260244, 2025).